IL10 (interleukin 10)
Diseases named in the same sentence as IL10 in open-access papers (continued):
Sharing a sentence is not in itself a finding about the gene and the disease.
tuberculosis (continued). "Current results from our group indicate that a higher percentage of CD4+ cells express Notch1 in patients who are clinically cured of tuberculosis, a condition that is characterized by increased IFN-γ and IL-10." (PMID 26495323, 2015). "Our study evaluated the mRNA and cell surface expression of TLR2 and TLR4; iNOS expression; and the production and expression of IL-12, IFN-γ, TNF-α, IL-17, IL-10 and TGF-β in pulmonary tuberculosis patients during anti-tuberculosis treatment." (PMID 24558401, 2014). "It is known that IL-10 suppresses macrophage and DC functions through the suppression of IL-12, IFN-γ and MHC II expression during tuberculosis." (PMID 24695099, 2014). "Our results showed that the production of anti-inflammatory cytokines, such as IL-10 and TGF-β, tended to rise during anti-tuberculosis treatment and to diminish at the end of treatment." (PMID 24558401, 2014). "CXCL10 and TNF-α may be used as adjunct markers alongside an IFN-γ release assay to diagnose M. tuberculosis infection, and IL-17 and IL-10 production may differentiate individuals with LTBI from active TB." (PMID 24260295, 2013). "In our study, we further determined the values of IL-4, IL-10 and other related cytokines specifically in anergic tuberculosis patients, which were significantly higher than in TST-positive tuberculosis patients and may be associated with the etiology of anergic tuberculosis." (PMID 23936496, 2013). "On the contrary, higher frequencies of IL-10 producing cells were found in γδ DN T-cells from TB-infected patients, due to the severe form of tuberculosis, which together with the lower IFN-γ production suggest a modulatory role of γδ DN T-cells during tuberculosis." (PMID 23239994, 2012). "IL10 acted to restrain the extent to which macrophages produced iNOS and TNF-alpha, two critical mediators of host control of tuberculosis." (PMID 22359543, 2012). "Clinically, similar findings were noted in reactivating tuberculosis patients on anti-TNF therapy who presented with a decreased T cell activation profile and reduction in IFNγ and IL-10 synthesis." (PMID 22132068, 2011). "Furthermore, Th1 cell clones coproducing IFN-γ and IL-10 have been isolated from bronchoalveolar lavage (BAL) of active pulmonary tuberculosis (TB) patients." (PMID 19646904, 2009). "The CD patients with MAP infection in the TU/ACU study had elevated (IFNγ), TNFα and IL-17A like tuberculosis patients, but they did not have elevated IL-2, IL-5, IL-10 and GM-CSF typically reported in tuberculosis patients." (PMID 38415011, 2024). "The high expression of IL-10 and TGF-β1 in older patients may weaken their anti-tuberculosis immunity and treatment effectiveness." (PMID 38572322, 2024). "The high expression of IL-10 and TGF-β1 in the older group may have reduced their anti-tuberculosis immunity and treatment effectiveness." (PMID 38572322, 2024). "There were significant differences in IL10 produced when HTDY and LAM stimulated PBMC of tuberculosis patients again, and significant differences in IFN-γ produced when E6C10 stimulated PBMC of tuberculosis patients again." (PMID 37077246, 2023). "Notably, based on principal component analysis, IL-6, IL-10, pSTAT3, and SOCS3 were the most influential factors that distinguished tuberculosis patients from healthy controls." (PMID 34035497, 2021). "IFN-γ, IP-10, IL2R, and CXCL-9 showed high expression in latent and active tuberculosis patients (p = 0.001), with a decrease in IL10 expression, and no statistical difference in IL-4 levels among all the groups (p = 0.999)." (PMID 32962082, 2020). "Similarly, a previous study also reported that IL10 and IL2 accurately identified active tuberculosis from LTBI cases." (PMID 32962082, 2020).
tuberculosis (continued). "Moreover, we demonstrated that IL-27 and type I IFN signaling regulate IL-10 expression in T cells early during M. tuberculosis infection, providing new insights into the factors that regulate the production of IL-10 that suppresses protective immunity to TB." (PMID 28584007, 2017). "Overexpression of IL-10 by macrophages and monocytes (under control of the CD68 promoter) was shown to induce the expression of Arg1 and other markers associated with alternative macrophage activation during M. tuberculosis infection, increasing host susceptibility to TB." (PMID 27849167, 2016). "Additionally, tuberculosis (TB) disease might be accelerated by the immune suppressive cytokine IL-10." (PMID 26204894, 2015). "We also performed preliminary analysis of the cellular source of IL-10 and IL-22 and found both more frequently in CD14+ cells, consistent with increasing evidence that innate immune system activation is a component of the immunopathology of tuberculosis-IRIS." (PMID 23303806, 2013). "Analysis of corresponding serum samples showed significantly higher concentrations of IL-10 and IL-22 in tuberculosis-IRIS patients, compared with non-IRIS patients." (PMID 23303806, 2013). "TST-positive tuberculosis patients had higher IL-4 and IL-10 values than healthy controls, though the difference was not statistically significant (q = 1.043, 0.748, P = 0.299, 0.456)." (PMID 23936496, 2013). "However, no study appears to have been done to compare the monocytes of tuberculosis patients and healthy controls in their in vitro MGC forming ability with particular reference to the relative roles of IL-4 and IL-10." (PMID 24147054, 2013). "Our analysis of IL-10–related cytokines showed an increase in the transcript levels of IL-10 and IL-22 in tuberculosis-IRIS patients, compared with non-IRIS controls." (PMID 23303806, 2013). "Our data demonstrate that IL-10-secreting CD8+ T cells can arise during chronic Mtb infection, although the significance of this T cell population in tuberculosis pathogenesis remains unclear." (PMID 23472214, 2013). "During active tuberculosis, suppression of Mtb. specific T cell response is evidenced by decreased production of the cytokines such as IL-2 and interferon IFN-γ with simultaneous over production of suppressive cytokines such as IL-10 and TGF-β." (PMID 23028594, 2012). "Studies have shown elevated levels of IL-10 and TGF-β in tuberculosis (TB) patients’ serum and peripheral blood mononuclear cells (PBMCs)." (PMID 39003443, 2024). "Tuberculosis is highly endemic in Ghana and yet, to the best of our knowledge, this study is the first to directly compare plasma levels of cytokines (IL-10, IFN-γ and TNF-α) in MDR-TB and DS-TB patients in the country." (PMID 30583589, 2018). "IL-10 (and regulatory T cells) contributes to an equilibrium between inflammatory and anti-inflammatory responses in diseases such as mucosal Leishmaniasis and tuberculosis, but we did not observe IL-10 responses here." (PMID 30631322, 2018). "Interestingly, mouse models of tuberculosis have not only reported that the lack of IL10 is beneficial to the host in a mycobacterial infection, but also that an IL10 deficiency can have detrimental effects on immunological control." (PMID 29985419, 2018). "We also saw a tendency for TB cases infected with M. africanum to have increased TNF-α and IL-10 production compared to those infected with M. tuberculosis." (PMID 20811496, 2010). "Our data showed that mycobacterium tuberculosis (Mtb)-specific IFN-γ, TNF-α, IL-2, IL-6, IL-10, IL-5, IP-10, IL-1Ra, CXCL-1 and MCP-1 responses based on QFT-Plus significantly differed between Mtb-infected (including ATB, LTBI and previous TB) and uninfected healthy populations." (PMID 38166667, 2024).
tuberculosis (continued). "As blocking IL-10 enhances protection by BCG vaccination against M. tuberculosis infection, our findings indicate that interference with Mincle signalling can improve the protective capacity of BCG or TDB-containing adjuvant-based subunit vaccines against TB." (PMID 26939595, 2016). "The role of IL-10 in tuberculosis is controversial and there is an increasing body of evidence suggesting that the relationship between Th1 cytokines and IL-10 is not as antagonistic as it was first believed, and that these cytokines may complement each other in infectious diseases." (PMID 23824716, 2013). "Higher production of IL-10 and IL-17 in response to ESAT-6 was observed in the spouses compared with TB patients while the ratios of IFN-γ/IL-10 and IFN-γ/IL-17 in response to M. tuberculosis-derived PPD were significantly higher in TB patients compared with the spouses." (PMID 24260295, 2013). "Therefore, we believe that an increased persistent level of IL-6 expression in the cohort of HIV/TB patients against the background of ART and reduced concentrations of IL-4 and IL-10 can serve as a possible marker of early detection of M. tuberculosis infection in HIV-infected individuals." (PMID 34835417, 2021). "Although T cell-specific IL-6/IL-10 secretion has not been determined in TB-IRIS, triggers similar to those in acute tuberculosis patients may be assumed." (PMID 34035497, 2021). "Likewise, it has been reported that plasma levels of IL-10 and TGFβ are higher in DR-TB than in DS-TB patients, and recent reports have shown that extensively Drug-resistant tuberculosis (XDR-TB) patients with failed anti-TB therapy had increased the frequency of Treg compared to DS-TB." (PMID 34261449, 2021). "Induction of IL-2, IL-6, IL-10 (not shown), IL-17A, IFN-g and was higher in participants with BCG scars, but only IL-6 were induced more in participants with no past history of tuberculosis." (PMID 29680481, 2018). "Distinct genetic loci may also play a role in the observed spectrum of M. tuberculosis infection phenotypes in humans with recent candidate gene case–control studies identifying polymorphisms in IL10 and TLR9 associated with latent TB but not active TB." (PMID 28646863, 2017). "IL-10 levels were significantly higher in unstimulated non-IRIS cultures (P = .04) and increased more in tuberculosis-IRIS cultures, compared with non-IRIS cultures, after stimulation." (PMID 23303806, 2013). "P3 had a history of treated tuberculosis many years earlier and was the only non-IRD patient to exhibit higher production of IFNγ than IL-10." (PMID 18442415, 2008). "However, in contrast to tuberculosis patients, the CD patients in the TU/ACU study did not have statistically significant increased IL-2, IL-5, IL-10, and GM-CSF." (PMID 38415011, 2024). "Additionally, co-infection with the non-lethal P. yoelii also resulted in more severe tuberculosis pathology with increased immune cells infiltration, and increased pro-and anti-inflammatory mediators, mainly IFN-γ, TNF-α, IL-6, IL-10, and IL-17." (PMID 36504775, 2022). "The higher level of IFN-γ/IL-4 and IFN-γ/IL-10 in HIV negative TB cases is expected where a Th1 type immune response dominates after clearance of the actively multiplying bacteria and resolution of the disease by the anti-tuberculosis treatment." (PMID 24592945, 2014). "Among PLWH with a history of tuberculosis (TB), a significant negative correlation was observed with IL-1β and IL-10 levels, indicating lower interleukin levels in PLWH with skin disorders and a history of TB." (PMID 40572779, 2025). "Interestingly, while αβ and γδ DN T-cells from patients with non-severe tuberculosis display a pro-inflammatory cytokine profile, characterized by enhanced IFN-γ, the γδ DN T-cells from patients with severe disease express a modulatory profile exemplified by enhanced interleukin-10 production." (PMID 23239994, 2012).
tuberculosis (continued). "The ratio of IFN-γ/IL-10 and IFN-γ/IL-4 showed a significant increase after treatment in HIV negative TB cases but not in HIV positive TB cases which might indicate prolonged impairment of immune response to TB in HIV positive TB patients as compared to HIV negative tuberculosis patients." (PMID 24592945, 2014).
pneumonia (175 papers, 2005 to 2026). An acute, acute and chronic, or chronic inflammation focally or diffusely affecting the lung parenchyma, caused by an infection in one or both of the lungs (by bacteria, viruses, fungi, or mycoplasma.). "IL-10 demonstrated exceptional diagnostic performance with significantly elevated serum levels in pneumonia cases and optimal discrimination at a threshold >73.18 pg/ml (100% sensitivity and specificity)." (PMID 41018059, 2025). "Severe pneumonia was associated with higher IL-10 and PCT levels (both serum and saliva), younger age, elevated heart rate, and higher CRP." (PMID 41018059, 2025). "In this study, we used mice with myeloid cell specific deletion of IL-10R to investigate the cellular targets of IL-10 immune suppression during infection with Streptococcus pneumoniae, the most common bacterial cause of pneumonia." (PMID 37381945, 2024). "In subsequent traffic jams after removal of SII and age, the following were significantly associated with rehabilitation time: gender (β = −0.27), pneumonia (β = 0.359), and IL-10 (β = −0.21)." (PMID 39335569, 2024). "The IL10 rs1800896 (-1082 G/A) polymorphism has been found to be associated with greater IL10 serum levels and an increased risk of developing severe pneumonia." (PMID 36882862, 2023). "Our results are in line with a previous study performed in a cohort of patients with IPD and pneumonia, in which an IL-10 polymorphism was also associated with severity, with the development of septic shock due to an enhanced IL-10 release." (PMID 38143267, 2023). "Serum IL-6 and IL-10 have been suggested to be directly associated with the development of pneumonia symptoms, and their expression levels in the serum can indirectly reflect the development of pneumonia in vivo." (PMID 37764047, 2023). "An earlier study on IL-10 genetic polymorphism had reported an association of rs1800896 (− 1082 G/A) SNP with higher IL-10 serum levels and an increased risk of pneumonia severity." (PMID 37521849, 2022). "It is important to note that the involvement of neutrophils in IL-10 production is different among the broad range of pathogens able to cause pneumonia." (PMID 33995357, 2021). "In murine pneumonia caused by Streptococcus pneumoniae or Klebsiella pneumoniae, the anti-inflammatory cytokine IL-10 ameliorated the bacterial clearance from the lung." (PMID 34959964, 2021). "Some reports have shown that inactivation of IL-10 is linked to an increased risk of developing pneumonia." (PMID 32805728, 2020). "Severe pneumonia patients have shown increased serum levels of IL-6, IL-8 and IL-10, and the excess of IL-6 and IL-10 are associated with an increase in mortality from 4.8% to 11.4%." (PMID 28617807, 2017). "A subset analysis after removing studies that were not consistent with HWE equation revealed a borderline significance for the association of the IL10 rs1800896 GA/AA genotype with susceptibility to pneumonia/pneumococcal disease." (PMID 27725770, 2016). "IL-10 levels were also high in patients with pneumonia and were associated to lymphocytosis (P = 0.025)." (PMID 27905908, 2016). "In particular, high levels of interleukin (IL)-6, IL-8, and IL-10 have been detected in patients with severe pneumonia and excess IL-6 and IL-10 was associated with increased mortality (from 4.8 to 11.4 %)." (PMID 27716262, 2016). "Published data on the associations between three well-characterized polymorphisms in the interleukin 6 and 10 (IL-6 and IL-10) genes and the risk of pneumonia are inconclusive." (PMID 25708204, 2015). "To generate more information, we carried out a meta-analysis of all of the available case-control studies to investigate the association of genetic polymorphisms of IL-6 and IL-10 with the risk of pneumonia." (PMID 25708204, 2015). "This study revealed that IL-10 -819 polymorphism is associated with postoperative pneumonia in Japanese patients with esophageal cancer." (PMID 24804995, 2014).
pneumonia (continued). "Only IL-10 -819 polymorphism was significantly associated with pneumonia (p = 0.0334, OR = 2.68, 95 % CI = 1.08–6.67)." (PMID 24804995, 2014). "Among the cytokine promoter gene polymorphisms analyzed, a significant association with pneumonia was found for IL-10 -819 T/C." (PMID 24804995, 2014). "Multivariate analysis of factors such as sex, smoking, length of operation, field of lymph node dissection, and IL-10 polymorphism identified IL-10 polymorphism as independent predictor of postoperative pneumonia." (PMID 24804995, 2014). "Presence of the IL-10 -819 TT genotype seems to confer lower IL-10 release in response to surgical stress and an increased risk of postoperative pneumonia." (PMID 24804995, 2014). "Conversely, excessive IL-10 elevation may indicate compensatory immunosuppression and predispose patients to infectious complications such as pneumonia or urinary tract infections." (PMID 40869247, 2025). "Patients with IL-10 -819 T/T genotype may be at high risk for postoperative pneumonia after esophagectomy." (PMID 24804995, 2014). "In addition, systemic increase in IL-6 and IL-10 in pneumonia is associated with the worse prognosis." (PMID 24696530, 2014). "As systemic IL-10 is associated with S. pneumoniae persistence, the improved pathogen clearance in LysMcrexIL-10Rflox mice, despite the availability of systemic and pulmonary IL-10, suggests that IL-10R suppresses myeloid cell–mediated protection against S. pneumoniae lung infection." (PMID 37381945, 2024). "As lack of IL-10 causes impaired clearance of bacteria leading to a more destructive cause of pneumonia, therefore, this elevated IL-10 in the combined antibiotic treated mice might be essential for efficient elimination of bacteria and therapy for protection against pneumococcal pneumonia." (PMID 24565171, 2014). "Median serum IL-10 was 379.1 pg/ml (IQR: 265.7–602.8) in children with pneumonia, dramatically higher than 66.03 pg/ml (IQR: 57.45–67.49) in healthy controls (p < 0.001)." (PMID 41018059, 2025). "Together, these subgroup comparisons suggest that while all three markers (IL-6, IL-10, PCT) rise in the presence of pneumonia, only IL-10 and PCT levels (in both serum and saliva) correlated with disease severity, whereas IL-6 did not." (PMID 41018059, 2025). "Among the biomarkers, high serum IL-10 was the most powerful cytokine predictor of severity (OR = 5.75, 95% CI: 2.80–11.70, p < 0.001), indicating that children with markedly elevated IL-10 had nearly six-fold higher odds of developing severe pneumonia." (PMID 41018059, 2025). "Salivary IL-10 >77.6 pg/ml achieved 100% specificity with a slightly lower sensitivity (88.0%), indicating that while nearly all healthy children had salivary IL-10 below this level, a few milder pneumonia cases fell below the cutoff." (PMID 41018059, 2025). "Our study found a notable link between high salivary IL-10 levels and severe pneumonia (p = 0.0437)." (PMID 41018059, 2025). "Salivary and serum IL-6, IL-10, and PCT show promising diagnostic potential for pediatric pneumonia when compared to healthy controls." (PMID 41018059, 2025). "Pro-inflammatory cytokines, such as IL-6 and IL-10, increase in patients with pneumonia according to disease severity." (PMID 40807081, 2025). "Statistically significant variables included gender (β = −0.28), pneumonia (β = 0.363), IL-10 (β = −0.21), and smoking status (β = −0.20)." (PMID 39335569, 2024). "After removing the next factor, namely, IL-6, statistically significant results were gender (β = −0.27), pneumonia (β = 0.357), and IL-10 (β = −0.21)." (PMID 39335569, 2024). "Further, molecular docking dynamics simulation revealed three key active components of IL10 induced by Dang-Shen-Yu-Xing decoction against Mycoplasma bovis pneumonia." (PMID 39380772, 2024).